CCL15 (C-C motif chemokine ligand 15)
Diseases named in the same sentence as CCL15 in open-access papers (continued):
Sharing a sentence is not in itself a finding about the gene and the disease.
melanoma (2 papers, 2025). A malignant, usually aggressive tumor composed of atypical, neoplastic melanocytes. "Moreover, CCL15 is also important in regulating the progression of melanoma and pancreatic cancer." (PMID 40740234, 2025). "Interestingly, an experiment in which melanoma cells were introduced into the bloodstream of mice while CCL8 and CCL15 were administered subcutaneously, resulted in an increased number of tumor cell colonies embedded in the lungs, suggesting important function of those chemokines in metastasis." (PMID 40725022, 2025).
thyroid (2 papers, 2016 to 2025). "Measurement of TAMs and CCL15 in follicular thyroid lesions may be applied clinically to differentiate FTC from FA pre-operation." (PMID 26875556, 2016).
thyroid cancer (2 papers, 2018 to 2021). "Most chemokines were downregulated in thyroid cancer, including CCL3, CCL4, CCL15, CCL21, and CXCL13." (PMID 33414407, 2021). "At present, CCL2, CCL15, CCL20, CXCL1, CXCL8, CXCL12, and CXCL16 are the main chemokines showing a role in thyroid cancer." (PMID 29977225, 2018). "Studies taking into account the role of CCL15, C–X–C motif ligand 12, CXCL16, CXCL1, CCL20, and CCL2 in the context of thyroid cancer will be reviewed with particular emphasis on CXCL8." (PMID 29977225, 2018).
atrial fibrillation (1 paper, 2024). A disorder characterized by an electrocardiographic finding of a supraventricular arrhythmia characterized by the replacement of consistent P waves by rapid oscillations or fibrillatory waves that vary in size, shape and timing and are accompanied by an irregular ventricular response. "We observed MR evidence for associations between genetically regulated levels of 7 proteins and HF risk factors including: SPON1, CCL15, and ITIH3 with hypertension; SVEP1 and SPON1 with atrial fibrillation; FSTL3 and NRP1 with diabetes; and APOF, CCL15, ITIH3, and NRP1 with CHD." (PMID 38225249, 2024).
bladder cancer (1 paper, 2025). "LC1 tumours also showed modest enrichment for immune‐associated transcripts, including CCL15 and PSMB10, and elevated RNH1 expression, a gene previously linked to reduced invasion and metastasis in bladder cancer." (PMID 41425537, 2025).
chronic graft versus host disease (1 paper, 2022). Chronic graft versus host disease (GVHD) is a complication that can occur after a stem cell or bone marrow transplant in which the newly transplanted donor cells attack the transplant recipient's body. "Elevated levels of CCL15 and Ccl9 were found in lungs of patients and mice with chronic hypersensitivity pneumonitis and chronic graft-versus-host disease, respectively." (PMID 35625754, 2022).
Crohn disease (1 paper, 2010). A gastrointestinal disorder characterized by chronic inflammation involving all layers of the intestinal wall, noncaseating granulomas affecting the intestinal wall and regional lymph nodes, and transmural fibrosis. "CCL15/MIP-1δ has been shown to be expressed constitutively in the intestinal epithelial cells and play a role in chronic inflammatory pathologies of the intestine such as Crohn's disease and ulcerative colitis." (PMID 21092330, 2010).
delirium (1 paper, 2023). A disorder characterized by confusion; inattentiveness; disorientation; illusions; hallucinations; agitation; and in some instances autonomic nervous system overactivity. "Again, delirium was associated mostly with higher expression, but the inverse was true preoperatively for myoglobin (MB), IL-2, and IL-20, and postoperatively for chemokine ligand 15 (CCL15) and TNF-related apoptosis-inducing ligand (TRAIL)." (PMID 37156856, 2023).
diabetes (1 paper, 2024). "We observed evidence of colocalization for observed MR associations for SPON1, CCL15, and FSTL3 with multiple outcomes; for SVEP1 with HF; and for NRP1 with diabetes and CHD." (PMID 38225249, 2024).
encephalitis (1 paper, 2023). An acute inflammatory process affecting the brain parenchyma. "For LGI1 encephalitis patients (n = 6) and HDs (n = 4), miR-2467-5p expression in PBMCs was negatively associated with the serum levels of PDCD1 (r = −0.867, p = 0.002) and CSF3 (r = −0.721, p = 0.023), but favorably correlated with the serum level of CCL15 (r = 0.746, p = 0.017)." (PMID 37644514, 2023). "The patients with LGI1 encephalitis with CSF-restricted OCBs exhibited higher level of CCL15 alone compared to those patients without CSF OCBs (p < 0.05)." (PMID 37644514, 2023). "Then, bioinformatics algorithms uncovered the probable miR-2467-5p binding sites in the 3'untranslated region (UTR) of CSF3' and PDCD1' mRNA, and a negative correlation was found between PDCD1 expression and CCL15 expression in the serum of LGI1 encephalitis patients (r = −0.546, p = 0.013)." (PMID 37644514, 2023). "Mechanically, miR-2467-5p significantly induced reduced expression of CSF3 and PDCD1 by binding with their 3`UTR while enhanced CCL15 expression, but not significantly correlated with peripheral blood CD19 + B cell proportion of LGI1 encephalitis patients." (PMID 37644514, 2023).
gastric tumor (1 paper, 2021). "Previous studies have preliminarily indicated that CCL15 expression is higher in gastric tumor tissues than in normal tissues." (PMID 33710810, 2021).
head and neck cancer (1 paper, 2020). A primary or metastatic malignant neoplasm affecting the head and neck. "Other significantly elevated cytokines detected in the saliva of head and neck cancer patients included CX3CL1, CCL2, CXCL1 and CCL15, most of which correlated with UWS secretion rates and objective oral dryness (CODS)." (PMID 32911805, 2020).
liver disease (1 paper, 2022). "A number of these analytes were differentially expressed related to liver disease, including proteins with inflammatory and immunomodulatory activities, such as CCL15, pentraxin-3, TRAIL and MMP-3, among others, as well as the growth factors M-CSF, SCF, SCFG-β and HGF." (PMID 36230823, 2022).
lung diseases (1 paper, 2023). "Murine CCL6 shares homology with human CCL23/CCL15, which perform the similar roles in lung diseases." (PMID 36934284, 2023).
lymph node metastasis (1 paper, 2021). "Subgroup analysis indicated that patients with high CCL15 expression showed more lymph node metastasis than those with low CCL15 expression (P < 0.05)." (PMID 33710810, 2021).
myocarditis (1 paper, 2024). Myocarditis is a condition that is characterized by inflammation of the heart muscle (myocardium). "Additionally, the researchers found that the levels of N-terminal prohormone of brain natriuretic peptide (NT-proBNP) and Chemokine (C-C motif) ligand 15 (CCL15) were higher in children with MIS-C related myocarditis." (PMID 39457139, 2024).
neurosyphilis (1 paper, 2016). Infection of the brain or spinal cord by Treponema pallidum. "CSF CCL20, CCL15 and CXCL5 levels were down-regulated in neurosyphilis patients compared to those of non-neurosyphilis patients (with at least a 0.65-fold decrease, p < 0.05)." (PMID 27650493, 2016).
Rotavirus infection (1 paper, 2017). Infection with any of the rotaviruses. "Of interest, several IFN inducible genes (OAS1, MX1, IL18, IITP3, TAP1, and RSAD2) as well as several cytokines and chemokines (CCL5, CXCL10, CXCL11, IL8, and CCL15) were upregulated by rotavirus infection." (PMID 28210256, 2017).
Thyroid adenoma (1 paper, 2023). The presence of a adenoma of the thyroid gland. "Furthermore, FTC can secrete the CCL15 chemokine to recruit TAMs and construct a tumor microenvironment, while CCL15 expression is low in thyroid adenoma." (PMID 37345200, 2023).
tumor (73 papers, 2008 to 2025). "The combination inhibited CCL15 expression in M2 tumor-associated macrophages and suppressed CCR1 expression on HNSCC cells, suggesting a cooperative immunomodulatory mechanism." (PMID 41156128, 2025). "Among these, CCR1 is considered the primary receptor mediating the tumor-promoting effects of CCL15, and it has been implicated in cancer metastasis, drug resistance, and progression." (PMID 40740234, 2025). "Cross-cohort correlation analyses demonstrated a robust association between TMs and the chemokine CCL15, a fibroblast-and tumor-derived factor implicated in immune recruitment and suppression." (PMID 40630945, 2025). "In this case, CCL15 causes osteoclastogenesis, which is followed by bone remodeling around the tumor cell and the formation of a metastatic niche." (PMID 33182504, 2020). "Both CCR1 and CCL15 were markedly overexpressed in ESCC tissues compared to adjacent non-tumor tissues." (PMID 40740234, 2025). "To investigate the mechanism by which CCL15-CCR1 axis promotes ESCC progression, we conducted a tumor-related gene PCR array analysis in EC109 cells following CCL15 and CCR1 knockdown." (PMID 40740234, 2025). "Tumor cells can secrete chemokine (C-C motif) ligand 15 (CCL15) to recruit C-C motif chemokine receptor 1 (CCR1)-positive macrophages, thereby facilitating immune evasion and promoting tumor progression." (PMID 40740234, 2025). "Our experiments in this study preliminarily revealed that FAAH affects tumor-stroma interactions by regulating CCL15 secretion, but the effect of immune cell recruitment needs to be further validated." (PMID 40630945, 2025). "Collectively, these results demonstrate that CCL15 promotes ESCC progression by acting on tumor-intrinsic CCR1." (PMID 40740234, 2025). "To extend our findings to human samples, we performed immunofluorescence double staining of α-SMA and CCL15 in tumor tissues and adjacent paracancerous tissues derived from patients with HCC." (PMID 38291436, 2024). "Compared with paracancerous tissues, the number of α-SMA+ fibroblasts expressing CCL15 evidently increased in tumor tissues." (PMID 38291436, 2024). "Cytokines such as CCL17 and CCL15 expressed from TAMs attract regulatory T cells (T regs) into the tumor stroma, whereas IL-10 and TGF-β suppress T-cell-mediated anti-tumor immune responses." (PMID 38672714, 2024). "Some chemokines described in this review, including CCL2, CCL5 and CCL15, can also recruit effector cells (including NK cells, T lymphocytes) that are critical for tumor clearance." (PMID 36173487, 2023). "In other cancers, the chemokine CCL15 has been linked to tumor-associated macrophage recruitment and CCL18 has been linked to an immunosuppressive tumor microenvironment, allowing for evasion of the host’s immune system." (PMID 37895248, 2023). "CCL15 can also promote immune system evasion by recruiting monocytes, which in turn, become tumor-educated and accelerate tumor invasion and metastasis." (PMID 36661524, 2023). "Elevated levels of CCL15 in serum and tumor tissue resulted in the accumulation of TAMs in tumor tissues." (PMID 36173487, 2023). "Among those genes that dominated at the end of development trajectory, we noted that CCL15, an oncogenic chemokine, accumulated along the pseudo-time trajectory and was identified to facilitate the formation of tumor ISME." (PMID 35673582, 2022). "A recent survey of tumor tissues from patients with GBM correlated the infiltrative character of GBM malignant cells with an increased expression of CCL15, CCL17, CD209, and TNF-α genes." (PMID 35992881, 2022). "CCL15 has been shown to play a critical role in tumor progression in various cancer types, including liver and colorectal cancers." (PMID 33710810, 2021). "Some chemokines were increased in LSCC samples, such as CCL2, CCL15, CCL16, and these chemokines were implicated in the angiogenesis or angiostasis balance and promoted tumor infiltrating hematopoietic cells in the pathophysiology of NSCLC." (PMID 33005178, 2020).
tumor (continued). "MCs accumulate into tumor microenvironment by the help of tumor cell-released chemoattractants such as SCF or CCL15." (PMID 31256327, 2020). "In this study it was concluded that CCL15 deletion was associated with diminished CCR1+ cell accumulation in the tumor and limited tumor growth." (PMID 34458892, 2020). "MC accumulation within the tumor microenvironment (TME) is mediated by SCF and CCL15 released from tumor cells." (PMID 32086776, 2020). "An orthotopic transplantation tumor model of HCC in nude mice established by 97H-CCL15-shRNA cells attracted fewer systematically delivered human bone marrow-derived MSCs, further demonstrating the induced migration effect of CCL15." (PMID 30593276, 2018). "Collectively, these data suggested that FTC tumor cell-derived CCL15 played an important role in recruiting macrophages in FTC." (PMID 26875556, 2016). "Although previous studies on the CCL15-CCR1 axis have predominantly focused on tumor-derived CCL15 recruiting CCR1+ immune cells, our findings revealed that CCR1 is expressed at significantly higher basal levels in ESCC cells compared to normal esophageal epithelial HET-1A cells." (PMID 40740234, 2025). "Among these chemokines, CCL15 has been found to be highly expressed in a variety of tumor tissues." (PMID 40740234, 2025). "Furthermore, NFKBIA upregulation suppresses NF-κB survival signaling and activates SRC-FHIT tumor-suppressive pathways, and CCL15 downregulation diminishes chemotactic and angiogenic activity." (PMID 41465234, 2025). "Importantly, CCR1 knockdown reversed the tumor-promoting effects of CCL15, providing strong evidence that CCL15 exerts its oncogenic role in ESCC primarily through CCR1 activation." (PMID 40740234, 2025). "Additionally, subcutaneous xenograft experiments in nude mice verified that CCL15 promotes tumor growth in vivo." (PMID 40740234, 2025). "The expression of the chemokine CCL15 displayed a positive correlation with disease progression, and the deconvolution results revealed a highly positive correlation between the proportion of tumour cells and the proportion of TREM2+ macrophages." (PMID 37994257, 2024). "CCL15 expression level in tumor tissues was also higher than that in HCC paracancerous tissues." (PMID 38291436, 2024). "For instance, the loss of SMAD4 in intestinal epithelial cells has been shown to result in the upregulation of chemotactic factors, including Ccl9, CCL15, or CXCL1/8, and thereby induces the recruitment of tumor promoting myeloid-derived cells or tumor-associated neutrophils." (PMID 37190048, 2023). "We found that overexpressing CCL15 can increase the vitality and tumor growth of xenograft tumors." (PMID 35673582, 2022). "Moreover, the expression level of CCL15 is upregulated in tumor tissues of HCC, and the expression level of CXCL12 is deregulated in HCC (R = 0.269, p = 1.45e-07; R = −0.23, p = 7.45e-06, respectively), which are consistent with PPIA expression changes." (PMID 33790943, 2021). "CCL15 also acts on non-cancer cells in the tumor, for example causing angiogenesis mediated by CCR1 and CCR3 on vascular endothelial cells." (PMID 33182504, 2020). "Accumulating evidence has suggested that CCL15, a member of the CC chemokine family and expressed only in the gut and the liver, may have a crucial role in the progression of tumor cells via the CC chemokine receptor." (PMID 30979374, 2019). "However, it remains unclear whether CCL15 secreted by tumor cells can also act directly on CCR1 expressed on the same tumor cells to exert tumor-regulatory effects." (PMID 40740234, 2025). "However, whether CCL15 can directly activate CCR1 expressed by tumor cells themselves to drive tumor progression remains unclear." (PMID 40740234, 2025). "Moreover, M2-phenotype TAMs promote tumor cell resistance through paracrine CCL15." (PMID 36173487, 2023).
tumor (continued). "Interestingly, in human CRC samples, CCL15 (the human orthologue to murine CCL9) expression appears to be inversely correlated with SMAD4 expression, and increased tumor CCL15 expression is associated with a three-fold increase in CCR1+ immune cell infiltration." (PMID 33834163, 2019). "Here, we discovered that both CCL15 and CCR1 are significantly overexpressed in tumor tissues of patients diagnosed with ESCC." (PMID 40740234, 2025). "Another chemokine signalling axis, CCL15 -CCR1 also activates NF-κB pathway by recruiting monocytes, eosinophils and neutrophils to the tumour site ultimately inducing drug resistance." (PMID 40852716, 2025). "The attraction of MCs to a tumor requires the action of different chemokines produced by the tumor cells such as the stem cell factor (SCF), CXCL2, CCL2, CCL5, CCL11, CXCL12, CCL15, IL-3, and IL-33." (PMID 41465542, 2025). "Mechanistically, CCL15 interacts with multiple chemokine receptors, especially CCR1, to recruit macrophages, neutrophils, and lymphocytes, thereby regulating tumor growth 6, 9-11." (PMID 40740234, 2025). "Several studies have also shown that the recruitment of CCR1+ myeloid cells via CCR1 ligands, such as CCL2, CCL9 and CCL15, promotes invasion, metastasis, and angiogenesis in CRC and other tumor types." (PMID 38750114, 2024). "The influx of mast cells into TME is mediated by tumor-cell-released chemoattractants, such as SCF or CCL15, and then mast cells can actively participate in the elimination of tumor cells through secreted histamin, TNF-α, and IL-1, IL-4 and IL-6." (PMID 38287290, 2024). "In livers of nude mice, SMAD4-deficient human CRC cells (AA/C1, HT29, Colo205, LoVo, DLD-1, and HCT116) displayed CCL15 upregulation and increase in CCR1(+) cells recruitment that promoted tumor invasion." (PMID 37185750, 2023). "The mechanisms of the disease progression included CCL15-mediated autocrine stimulation of the tumor invasion and recruitment of CCR1+ cells, of which 80% were CD14+ monocytes inducing activity of pro-tumor factors and accelerating metastasis." (PMID 37185750, 2023). "We observed that the expression levels of CCL15 and PPBP were downregulated in tumor tissues compared with the adjacent normal tissues." (PMID 36118890, 2022). "have suggested that the deletion of Smad4 in CRC promotes the expression of CCL15 and recruits more CCR1+ TANs and matrix metalloproteinase-9 to the metastatic site to form the premetastatic niche of disseminated tumor cells." (PMID 35912260, 2022). "This activity occurs through C-C motif chemokine ligand 15 and C-C motif chemokine receptor 1 (CCL15-CCR1), promoting tumor growth and cell progression." (PMID 34769401, 2021). "Several cytokine mRNAs' (CCL3/MIP-1α, CCL15/MIP-1δ, CXCL1, CXCL5/ENA78, CXCL8/IL8, CXCL9/MIG, CXCL10/IP10) were found to be overexpressed in the tumours while CCL15/MIP-1δ, CXCL5/ENA78 and IL8 mRNAs' were overexpressed in paired normals, as well." (PMID 21092330, 2010). "In contrast, EpCAM, IL8, CXCL10/IP10, CCL3/MIP-1α, CCL4/MIP-1β, CCL15/MIP-1δ, PDGFR-B were predominantly elevated in tumours compared to AN and PN." (PMID 21092330, 2010). "Similarly, CCL15 secreted from the xenografted orthotopic CRC model recruits CCR1+ MDSCs and leads to aggressive tumour growth." (PMID 40852716, 2025). "Notably, most studies to date have focused on the paracrine function of CCL15—namely, its role in recruiting CCR1+ immune cells to the tumor microenvironment." (PMID 40740234, 2025). "It has been demonstrated that tumor cells release inflammatory cytokines (IL-6, IL-1, TNF-α), chemokines (CCL2, CCL5, CCL15, CCL26), and growth factors (TGFβ), which ultimately recruit BMDCs such as myeloid-derived suppressor cells (MDSCs) and create a favorable niche for tumor development." (PMID 41383620, 2025).